PDPN (podoplanin)
Diseases named in the same sentence as PDPN in open-access papers (continued):
Sharing a sentence is not in itself a finding about the gene and the disease.
tumor (continued). "Parraffin-embedded sections of 16 tumours generated from PTRF-expressing or control PC3 cells were analysed by immunofluorescence using the lymphatic-specific marker podoplanin and the panendothelial cell marker endomucin." (PMID 24123650, 2013). "In malignant disease, the interaction between platelets and podoplanin via CLEC-2 induces a number of pathways involved in tumor cell migration and growth." (PMID 23840559, 2013). "The FC-IBC01 tumor emboli that expressed E-cadherin were enwrapped by lymphatic vessels, which are identified by specific staining for podoplanin (red fluorescence)." (PMID 24102046, 2013). "Consistently, immunohistochemistry of tumor sections with an antibody against the lymphatic endothelial cell marker Podoplanin showed a significant decrease in lymphatic vessel density at the periphery of tumors isolated from EGCG-treated mice." (PMID 24039951, 2013). "For example, we have reported that Src utilizes the focal adhesion adaptor protein Cas to induce PDPN expression in order to promote tumor cell migration." (PMID 22844530, 2012). "PDPN expression was more intense in tumor cells from control animals than animals treated with MASL." (PMID 22844530, 2012). "As FGF signaling has been shown to regulate endothelial VEGFR-3 expression, to avoid any underestimation of lymphatic vessel in the FGFR-DN group, podoplanin staining was also performed on tumor sections 3 weeks after implantation." (PMID 22761819, 2012). "PDPN regulates the activities of effectors including ezrin, Rho, and Cdc42 to mediate filopodia formation and promote tumor cell migration, invasion, and metastasis." (PMID 22844530, 2012). "One of the most differentially expressed genes in these cells was PDPN, and knockdown of PDPN in the VAFs abrogated their tumor-promoting effects." (PMID 22988448, 2012). "We have recently reported that the Src tyrosine kinase utilizes the adaptor protein Cas/BCAR1 to augment PDPN expression in order to promote tumor cell motility." (PMID 22844530, 2012). "PDPN expression is also increased on tumor cells, believed to promote tumor cell invasion and metastatic spread, and correlated with poor prognosis." (PMID 22884313, 2012). "While it is clear that PDPN plays an important role in tumor progression and metastasis, more mechanistic studies are needed to fully elucidate the function of this molecule." (PMID 22988448, 2012). "PDPN is also upregulated in tissue fibroblasts during inflammation, and PDPN-rich stroma is often observed in tumors, perhaps supporting the function of tumor-infiltrating leukocytes." (PMID 22884313, 2012). "PDPN is activated by endogenous ligands that bind to these extracellular carbohydrate moieties to induce tumor cell motility and metastasis." (PMID 22844530, 2012). "In the present research, the overall expression level of podoplanin in SACC tumor cells was low (only 13 samples had more than 10% expression)." (PMID 22580922, 2012). "Our data indicate that MASL be used to target PDPN in order to combat tumor cell growth and migration." (PMID 22844530, 2012). "Interactions between CLEC-2 and PDPN in tumors also likely play a role in tumor progression and metastasis due to platelets interacting with tumor cells." (PMID 22988448, 2012). "Normal salivary glands around the tumor revealed a positive cytoplasmic and/or membrane reaction with the podoplanin antibody; the positive cells were mainly located in myoepithelial cells and various zones of the secretory duct system." (PMID 22580922, 2012). "These included genes known to be expressed by microglia (CCL8, SPP1, IRF7, IL1RAP), macrophages (IL1RN, SPP1, PDPN, IL1RAP, MDK, TFRC, HRH4), and tumor-associated macrophages (IL6, SPP1)." (PMID 22937035, 2012). "The majority of data examining the function and signaling pathways of PDPN are from studies of PDPN overexpression in tumor cells." (PMID 22988448, 2012).
tumor (continued). "PDPN is widely used as a marker for lymphatic endothelial cells and fibroblastic reticular cells of lymphoid organs and for lymphatics in the skin and tumor microenvironment." (PMID 22988448, 2012). "Recently, it has been reported that podoplanin expression is upregulated in different human cancers, suggesting a role for podoplanin in tumor progression." (PMID 24551781, 2012). "Further studies from this group have examined the mechanism by which PDPN enhances the tumor-promoting effects of CAFs." (PMID 22988448, 2012). "Much of the mechanistic insight into PDPN biology has been gleaned from studies of tumor cells; tumor cells often upregulate PDPN as they undergo epithelial-mesenchymal transition and this upregulation is correlated with increased motility and metastasis." (PMID 22988448, 2012). "We can now add podoplanin expression as a shared characteristic of activated RA-FLSs and tumour cells that possibly affects common features of RA and carcinoma-like fibrotic tissue transformation and tissue invasion." (PMID 21385358, 2011). "A review of the pathology of the primary tumour in these two cases showed that both tumours contained intratumoural lymphatics, as assessed by endothelial cell expression of the lymphatic markers, podoplanin and LYVE-1." (PMID 22612847, 2011). "Instead, it resembled the strong whole cell surface-staining pattern of podoplanin in tumour tissues." (PMID 21385358, 2011). "Human podoplanin expression was immunohistochemically detected at the tumor cell surface in EBC1-P4-derived tumor tissue." (PMID 21034514, 2010). "Next, we examined the effect of podoplanin on the tumor growth and lymphogenous metastatic potential using a tumor implantation model as described in Methods." (PMID 21034514, 2010). "Podoplanin has also been found to promote tumour cell invasion by inducing collective cell migration via the down-regulation of the activities of small Rho family GTPases." (PMID 20196862, 2010). "Multivariate analysis using the Cox proportional hazards model included tumour site, T classification, nodal metastasis, stage, and degree of differentiation and podoplanin expression." (PMID 20196862, 2010). "Tumor cells invade into the lymphatic lumen which can be recognized by an enclose of podoplanin (D2-40)-positive endothelial cell." (PMID 20444291, 2010). "It has also been demonstrated that podoplanin contributes to tumour invasion by binding ERM proteins to activate RhoA resulting in epithelial-mesenchymal transition." (PMID 20196862, 2010). "These cases were studied by morphometry as well as IHC with tumor proliferation (Ki-67) and adhesion (E-cadherin) markers, myoepithelial (p63), as well as endothelial (podoplanin [D2-40], CD31, VEGFR-3, Prox-1) markers." (PMID 21297224, 2010). "There are contradictory data regarding the clinical significance and biological role of podoplanin expression in squamous cancers, with contrasting results depending on the tumour sites studied." (PMID 20196862, 2010). "The role of podoplanin in tumor cells, however, seems to be controversial in recent clinicopathological studies of human cancers." (PMID 21034514, 2010). "We also observed a trend towards better disease-specific survival for patients with a focal expression of podoplanin in the periphery of tumour nests, defined in some works as the invasive edge of the tumours." (PMID 20196862, 2010). "For statistical purposes, tumours with scores equal or lower than 6 (median value) were considered to have low podoplanin expression, whereas those with scores higher than 6 were considered high expression." (PMID 20196862, 2010). "Here, we investigated the role of podoplanin expressed in lung squamoid cancer cells (LSCCs) in experimental tumor progression." (PMID 21034514, 2010). "Using stable lung SCC cell line-derived transformants exogenously expressing podoplanin, we herein found direct evidence suggesting the role of podoplanin in experimental tumor progression." (PMID 21034514, 2010).
tumor (continued). "Using LYVE-1 and podoplanin staining, we identified LVs in all included MM specimens, both within the tumour itself and in the adjacent tissue." (PMID 19628489, 2009). "Since recent findings have focussed on podoplanin's potential role as a tumour progression factor, we aimed at identifying regulatory elements conferring PDPN promoter activity." (PMID 17343736, 2007). "Podoplanin becomes upregulated in cells of the invasive cancer front, where it induces filopodia formation and promotes tumour cell migration." (PMID 17343736, 2007). "Q-PCR showed a significant decrease in median podoplanin RNA from the control to the treated tumours." (PMID 17285134, 2007). "Due to its certain specificities and potential role in tumour progression, the regulation of PDPN gene expression is of high interest." (PMID 17343736, 2007). "In malignant astrocytic tumours, increased expression of podoplanin correlated with higher histological tumour malignancy." (PMID 17179989, 2007). "The control samples showed variable levels of podoplanin RNA (as seen by the interquartile range values), showing that lymphatic response is specific to the individual tumour/host." (PMID 17285134, 2007). "The excellent diagnostic performance of PDPN in ROC analyses (AUC > 0.97) reinforces its role not merely as a downstream marker but as a functional mediator of tumor progression." (PMID 41594182, 2026). "SRC enhances PDPN transcription through the focal adhesion adaptor protein Crk-associated substrate/Breast Cancer Anti-Estrogen Resistance Protein 1 (Cas/BCAR1), which promotes cytoskeletal reorganization and increases tumor cell motility." (PMID 41594182, 2026). "Notably, platelet glycoprotein VI (GPVI) interacts with tumor-derived galectin 3, integrin α6β1 binds to tumor ADAM9, CLEC-2 recognizes tumor podoplanin, and GPIIb/IIIa associates with tumor ανβ3 integrin." (PMID 40723273, 2025). "In small-cell carcinoma of the lung, Podoplanin-positive CAFs may inhibit tumor cell growth by secreting inhibitory cytokines or modulating immune cell activity." (PMID 40094065, 2025). "Additionally, PDPN+ CAFs transport the exosomal lncRNA FTX to tumor cells, activating the FTX–FEN1–ACSL4 axis to inhibit ferroptosis and potentiate invasiveness." (PMID 41430036, 2025). "Recently, a protocol using two markers, podoplanin (PDPN) and FAP, has been proposed for CAF identification; PDPN+ FAP− CAFs, as lymphoid tissue organizer phenotypes, identified the population that promotes and organizes tumor-associated TLS formation." (PMID 41154405, 2025). "CAF markers such as α-SMA, HGF, and podoplanin in tumor tissues could predict EGFR-TKI resistance.Targeting CAF-derived factors such as HGF or using antifibrotic agents may counteract TKI resistance." (PMID 40002883, 2025). "These associations were independently validated using a separate single-cell RNA-seq TCGA cohort (n=42), which demonstrated that PDPN modulates immune cell infiltration, suppresses cytotoxic immune cell functions, and inversely correlates with T cell accumulation within the tumor." (PMID 41573582, 2025). "Fourth, in advanced stages of disease, the masking effect between podoplanin and CLEC-2 has been proposed as a potential source of underestimation of free soluble CLEC-2 levels in plasma, particularly in patients with higher tumor burden or increased podoplanin expression." (PMID 41209555, 2025). "Beyond effects on tumor cells, PDPN also contributes to immune escape via the stromal compartment." (PMID 41573582, 2025). "Furthermore, as is widely recognized, positive PDPN signals were identified in the stromal lymphatic vessels of all three tumor types." (PMID 40428290, 2025). "Furthermore,through in vitro and in vivo experiments, we demonstrated that anti-tumor metabolites produced by F. rodentium can also modulate PDPN/CLEC-2/PI3K/AKT/mTOR signaling in CRC." (PMID 40693815, 2025).
tumor (continued). "Furthermore, the results of the immunohistochemical tests were validated and corroborated by the expression of the POSTN and PDPN genes at the mRNA level, which was detected in 100% (n = 28) of the tumours analyzed using the Real-time PCR method." (PMID 41361308, 2025). "PDPN expression was weak in 42 tumours (65.6%) and moderate in 7 tumours (11.0%)." (PMID 41361308, 2025). "PDPN can be considered a marker of neoplasia trending to generate metastases." (PMID 40677711, 2025). "PDPN could also act as a co-inhibitory receptor on T cells, and T cell specific PDPN conditional knockout mice exhibited delayed tumour growth." (PMID 39780187, 2025). "At the cellular level, the interactions of platelets with immune and tumor cells are key players, and activation of platelets in malignancy occurs by various stimuli, including podoplanin and thrombin, which facilitate tumor cell metastasis as consequence of tumor cell–platelet aggregate formation." (PMID 40694429, 2025). "Given that PDPN(+) CAFs indicate an activated state within the TME and that elevated PDPN levels correlate with tumor angiogenesis in GC, we hypothesize that PDPN‐expressing CAFs represent a subset that promotes angiogenesis." (PMID 39764562, 2025). "Recent evidence suggests that lymphatic vascular biomarkers such as the Vascular Endothelial Growth Factor (VEGF)-R3, LYVE-1, podoplanin, and Prox-1 (prospero-related homeobox-1) play crucial roles in promoting lymphangiogenesis and facilitating tumor dissemination to axillary lymph nodes." (PMID 40647432, 2025). "Interestingly, PDPN+ CAFs also exhibited a tumour-inhibitory effect by suppressing the proliferation of small cell lung cancer (SCLC) cells in a co-culture assay." (PMID 39780187, 2025). "Additionally, immunohistochemical staining revealed that the expression of PDPN on lymphocytes in the tumor tissues of the mice with CRC induced by AOM/DSS was dramatically increased." (PMID 40693815, 2025). "PDPN depletion impaired the ability of stromal cells to promote tumor cell proliferation." (PMID 40842027, 2025). "This behavior appears to be linked to the regulation of epithelial–mesenchymal transition (EMT) mediated by podoplanin, which confers tumor cells with a pro-migratory phenotype and provides an oncogenic advantage through the acquisition of the cancer hallmark “activating invasion and metastasis”." (PMID 41228241, 2025). "Moreover, when tumor cells are PDPN-positive, observing the corresponding site on the immunohistochemical slide using FE-SEM with the NanoSuit-CLEM method further enhances the accuracy of the differential diagnosis." (PMID 40428290, 2025). "Podoplanin and other procoagulants, such as polyphosphate, may be released by tumor cells in extracellular vesicles, as in the case of TF." (PMID 40725619, 2025). "Here, patients with an expression of podoplanin in viable tumor cells (‘podoplanin positive’) showed a significantly better prognosis (Log-rank (Mantel-Cox) test; p = 0.0399, x2 = 4.223); the analysis of CAFs did not play a prognostic role in any of the subgroups put to test." (PMID 40542163, 2025). "The binding of CLEC-2 to podoplanin expressed on tumor cells triggers platelet activation, aggregation, and the release of bioactive molecules that support tumor cell survival, adhesion to the vascular endothelium, extravasation to distant metastatic sites, and subsequent tumor growth 21-23." (PMID 41209555, 2025). "Furthermore, treatment with F. rodentium specifically decreased the expression of CLEC2 on tumor cells and PDPN on CD8+ T cells." (PMID 40693815, 2025). "Platelets form aggregates with tumor cells and are activated by tumor‐derived podoplanin." (PMID 40027151, 2025). "We hypothesized that NIR-PIT could allow selective depletion of PDPN+ cells within the TME and examined the efficacy of anti-PDPN NIR-PIT in a syngeneic MOC2 tumor model." (PMID 38275890, 2024).
tumor (continued). "PDPN utilizes ligand binding activity to regulate tumor cell metastasis, invasion, and migration." (PMID 40741180, 2024). "During the 2-year observation period, patients with high PDPN-expressing tumors had a 2.6-fold higher risk of mortality compared with patients with PDPN-negative tumors after adjusting for age, sex, and tumor type." (PMID 40741180, 2024). "We further evaluated the ADCC activity and antitumor effect against PDPN-positive tumor cells." (PMID 39594582, 2024). "It has also been shown that low levels of oxygen in SJ-1 and U87 spheroids increase PDPN expression, suggesting that hypoxia may contribute to tumor progression and invasion through increases in PDPN." (PMID 40741180, 2024). "We hypothesize that PDPN expression in PCFs of glandular tumors is primarily induced by tumor cell–PCF interactions." (PMID 39451200, 2024). "Furthermore, PDPN-activated CAFs led to the increased expression of tumor-promoting cytokines IL-6, IL-8, and CCL2." (PMID 40741180, 2024). "PDPN-expressing cells were observed predominantly at the tumor periphery, near the invasive front." (PMID 38275890, 2024). "A report in literature suggests that PDPN may be expressed on macrophages and could promote tumour invasion." (PMID 39619326, 2024). "Together, they contribute to PDPN-induced tumor metastasis and related cellular responses." (PMID 39682237, 2024). "PDPN‐positive CAF may have tumor‐suppressive effects in HGNEC, but the exact molecular mechanism remains to be elucidated." (PMID 39487962, 2024). "myCAFs are located in CAFs adjacent to tumor cells, while iCAFs marked by PDPN and/or COL14A1 are distant from tumor cells, where hypoxic and acidic environments being located in iCAFs putatively due to poor blood supply is consistent with HIF1A and GPR68 expressions." (PMID 38892190, 2024). "Moreover, PDPN-positive tumor cells exhibit a diverse pattern of invasion, such as ameboid invasion in melanoma and collective invasion in SCCs." (PMID 39594582, 2024). "The expression of PDPN is stimulated by tumor promoters like TPA, RAS, and Src." (PMID 39682237, 2024). "The results suggest that PDPN‐positive CAF in the TME may indirectly affect tumor immunity via increased PD‐L1 expression in the stromal immune cells." (PMID 39487962, 2024). "Additionally, tumor-expressed PDPN is the endogenous ligand of C-type lectin receptor (CLEC-2), a transmembrane protein expressed on platelets that is involved in platelet activation and agglutination." (PMID 38167452, 2024). "PDAC tumor cells release microparticles containing podoplanin, but the association between this protein and VTE has not yet been determined." (PMID 38891849, 2024). "Therefore, CAF‐expressing PDPN inhibited the proliferation of SCLC cells, indicating that CAF‐expressing PDPN are a tumor‐suppressive stromal cell component in SCLC." (PMID 39487962, 2024). "Binding of PDPN to CLEC-2 plays an important role in tumor growth and metastasis." (PMID 38504248, 2024). "In addition, the PDPN+ CAFs locate mainly in the superficial to deep area of the tumor, sparing the invasive front where tumor budding is often observed." (PMID 37143134, 2023). "The roles of cancer cell-derived PDPN in tumor progression have been well documented." (PMID 36671802, 2023). "According to functional research, PDPN encourages the growth of tumours." (PMID 38415034, 2023). "In the tumor microenvironment, the function of PDPN+ CAFs remains controversial." (PMID 37993428, 2023). "Recent studies have suggested that this marker could potentially be used to identify pro-tumorigenic fibroblast subpopulations, as presence of PDPN-positive fibroblasts correlated with worse outcomes across multiple tumor types." (PMID 38234683, 2023). "Functional research indicates that PDPN promotes the growth of tumours." (PMID 38415034, 2023).